UCHL5 (ubiquitin C-terminal hydrolase L5)
Diseases named in the same sentence as UCHL5 in open-access papers (continued):
Sharing a sentence is not in itself a finding about the gene and the disease.
tumor (continued). "UCHL5 level was significantly elevated in tumor tissues from LUAD and LUSC patients compared with normal lung tissues." (PMID 33046988, 2020). "Univariate regression analysis showed that tumor size, lymph node invasion, TNM stage and UCHL5 expression were associated with OS and DFS in patients with LUAD." (PMID 33046988, 2020). "UCHL5 was upregulated in 21 tissues (84%) and downregulated in 4 tissues (16%) out of 25 tumor tissues (p<0.001 by Fisher's exact test)." (PMID 33046988, 2020). "b-AP15 mediated inhibition along with siRNA knockdown of USP14 and UCHL5 induces synergistic apoptotic activity in MM tumor cells and overcomes resistance to bortezomib." (PMID 32354135, 2020). "Co-inhibition of USP14 and UCHL5 by novel DUB inhibitor VLX1570 revealed potent tumor-specific apoptotic activity in drug-resistant tumor cells of Waldenstrom macroglobulinemia (WM), an incurable non-Hodgkin lymphoma." (PMID 32354135, 2020). "Above all, Wnt/β-catenin pathway activation at least partly explained the tumor-promoting effects of UCHL5." (PMID 32596150, 2020). "Consistently, the overexpression of UCHL5 in EC tissues and cell lines was further confirmed by western blot (WB) and polymerase chain reaction (PCR) compared with non-tumor control." (PMID 32596150, 2020). "Consistently, the UCHL5 mRNA level was markedly elevated in 18 (75%) and decreased in 6 (25%) out of 24 tumor tissues in comparison with the controls (p<0.01 by Fisher's exact test)." (PMID 33046988, 2020). "Consistently, we observed decreased cyclin D1 and CDK4 levels and delayed cell growth in UCHL5 knocked down tumor cells." (PMID 33046988, 2020). "The results demonstrated that UCHL5 protein expression is significantly higher in tumor tissues in comparison with the control tissues from patients with NSCLC." (PMID 33046988, 2020). "It has been reported that USP14 and UCHL5 are involved in the development of tumor and are potential new targets for proteasome inhibition in DLBCL." (PMID 31694672, 2019). "A recent study, for instance, showed that USP14 and UCHL5 were detected in tumor cell cytoplasm in 77 and 74% of the DLBCL cases, respectively." (PMID 31694672, 2019). "b-AP15 inhibits USP14 and UCHL5 and was shown to inhibit tumor growth in multiple solid tumor mouse models and attenuated tumor invasion in acute myelogenous leukemia in in vivo models." (PMID 31396277, 2019). "A cytoplasmic and nuclear UCHL5 staining pattern was observable when present throughout the tumor tissue, and was of uniform intensity." (PMID 29474458, 2018). "In summary, we present compelling data on the targetability of the 19 S proteasome-associated DUBs, USP14 and UCHL5 with the use of VLX1570, which induces tumor-specific cell death, particularly in WM cells resistant to bortezomib or ibrutinib." (PMID 27813535, 2016). "Importantly, UCHL5 promotes glycolysis in keeping with our finding that CSCs show lower UCHL5 mRNA levels than the tumor bulk together with lower levels of glucose transporter and higher mitochondrial activity." (PMID 40597978, 2025). "Furthermore, b-AP15, a dual-targeting inhibitor of USP14 and UCHL5, promotes cell apoptosis and induces cell cycle arrest at the G2/M phase, as well as effectively suppresses tumor growth in nude mice." (PMID 40804247, 2025). "Furthermore, b-AP15, a dual-targeting inhibitor acting on USP14 and UCHL5, effectively suppressed tumor growth in nude mice." (PMID 40804247, 2025). "These outcomes demonstrated that UCHL5 can indeed promote tumor development in vivo." (PMID 38773433, 2024). "The findings demonstrated that the glycolysis route underwent the greatest multiple of change, which led us to speculate whether UCHL5 promoted tumor progression by regulating the glycolysis process." (PMID 38773433, 2024). "The results also found that UCHL5 significantly improved the glycolytic ability of tumor cells." (PMID 38773433, 2024). "Higher UCHL5 expression was mainly detected in cytoplasm of tumor cells." (PMID 33046988, 2020).
tumor (continued). "UCHL5 staining in tumor tissues was much stronger than that in controls." (PMID 33046988, 2020). "Finally, we assessed the UCHL5 effects on cell growth in the other tumor type and BEAS-2B lung epithelial cells." (PMID 33046988, 2020). "UCHL5 immunoexpression was evaluable in 490 (75.4%) of the tumor specimens." (PMID 29474458, 2018). "The knockdown of USP14 and UCHL5, or treatment with the inhibitor b-AP15, significantly impeded ATC cell proliferation, reduced metastasis capabilities, and suppressed tumor formation in nude mice models." (PMID 40804247, 2025). "Tumor-related signaling pathways that account on crucial adaptor degradation, including Wnt, NF-κB, and TGF-β are affected by UCHL5, theoretically." (PMID 39034372, 2024). "Predictably, images of the liver and H.E. staining showed that overexpression of SIAH1 inhibited tumor growth and intrahepatic metastasis, and immunohistochemistry was used to analyze the expression of SIAH1, ADRM1, UCHL5, FASN, and FSCN1." (PMID 39075049, 2024). "Twelve of the ninety-nine DUB genes were identified as differentially expressed in MB compared to non-tumor tissue (p < 0.0001) for the GO category of DNA repair in the Swartling dataset, including USP1, OTUB1, UCHL5, USP7, and PSMD14 (aka POH1)." (PMID 37892185, 2023). "Mechanistically, UCHL5 activates the AKT/mTOR signaling pathway and increases c-Myc expression, which promotes tumor occurrence and progression." (PMID 37497216, 2023). "The expression of OTUB1 and UCHL5 was significantly decreased (p < 0.001) in AS, GBM, and ODG compared to non-tumor tissue, while the expression of USP3 was significantly elevated (p < 0.001)." (PMID 37892185, 2023). "DUBs, ubiquitin carboxyl-terminal hydrolase L5 (UCHL5) and the ubiquitin-specific peptidase 14 (USP14), were detected in the cytoplasm of a high proportion of DLBCL tumor cells." (PMID 33923680, 2021). "b-AP15 (also known as VLX1500) inhibited the activity of the deubiquitinases, ubiquitin C-terminal hydrolase 5 (UCHL5) and USP14, inducing tumor cells apoptosis and inhibiting tumor progression." (PMID 31988639, 2020). "Univariate Cox regression analysis indicated that tumor size, lymph node invasion, TNM stage and UCHL5 level were correlated with OS and DFS in patients with LUAD." (PMID 33046988, 2020). "However, positive UCHL5 expression was a significant prognostic factor in both uni- and multivariable analysis in subgroups of patients with disease stages I-II (p = 0.028 and p = 0.001, respectively), and in patients with small (<5 cm) tumor size (p = 0.001 and p <0.001, respectively)." (PMID 29474458, 2018). "In concert, these data provide further validation of USP14 and UCHL5 as bonafide targets in WM and the ability of VLX1570 to reduce WM cell growth in tumor bearing mice while extending their survival." (PMID 27813535, 2016). "The remodeling of the tumor microenvironment may be one of the factors contributing to the promotion of RCC by UCHL3 and UCHL5." (PMID 39034372, 2024). "The results demonstrated that UCHL5 expression was upregulated in 64 (87.7%), unchanged in 6 (8.2%) and downregulated in 3 (4.1%) tumor tissues in comparison with the paired non-cancerous tissues out of 73 patients (p<0.0001, chi-squared test)." (PMID 33046988, 2020). "We also performed UCHL5 IHC staining on tumor tissues and paired non-cancerous control tissues (controls) of NSCLC patients." (PMID 33046988, 2020). "We first investigated UCHL5 expression in tumor and adjacent noncancerous control tissues from 25 patients with NSCLC by RT-PCR and western blot." (PMID 33046988, 2020).
tumor (continued). "Another small molecule b-AP15 is first reported as a new tumor cell inhibitor to 19S regulatory-particle-associated deubiquitinases USP14 and UCHL5 activity without affecting 20S core-particle-associated proteolytic activity." (PMID 26097878, 2015). "UCHL5 expression was detected in both tumor and paired non-cancerous tissues from 73 LUAD patients." (PMID 33046988, 2020). "Thus, the UCHL5 level was significantly elevated in NSCLC tumor tissues in comparison with non-cancerous tissues." (PMID 33046988, 2020). "Recently it was also established that targeted inhibition of USP14 and UCHL5 with the novel small-molecule proteasome inhibitor b-AP15 induced proteotoxic stress and apoptosis in tumor cells of WM, without affecting proteolytic activity of the 20S proteasome." (PMID 32354135, 2020). "Therefore, We selected PKCα as the target protein for USP14 and UCHL5 due to its prominence in the PPI network and the lack of prior research connecting USP14 to the PKC family, offering new insights into tumor biology mechanisms." (PMID 40804247, 2025). "Importantly, we observed cell growth is markedly inhibited in UCHL5 knocked down tumor cells but not in lung epithelial cell BEAS-2B, highlighting usefulness of UCHL5 as a potential therapeutic target for tumors." (PMID 33046988, 2020).
infection (7 papers, 2015 to 2023). The state of being infected such as from the introduction of a foreign agent such as serum, vaccine, antigenic substance or organism. "UCHL5 overexpression raised cell viability at different time points after lentiviral infection." (PMID 32596150, 2020). "In addition, increasing evidence indicates a role for UCHL5 in infection." (PMID 34431717, 2021). "The blocking activity of WP1130 is restricted to five DUBs; however, two of these enzymes, USP5 and UCHL5, are also targets of PR-619, which did not affect productive infection." (PMID 36851696, 2023).
neurodegenerative disease (2 papers, 2022 to 2025). A disorder of the central nervous system characterized by gradual and progressive loss of neural tissue and neurologic function. "Another member of the UCH subfamily thought to be involved in neurodegenerative disease due to its proteasomal association is UCHL5/UCH37." (PMID 35159365, 2022).
UCHL5 also shares sentences with these, for which no sentence is quoted: cervical carcinoma (3 papers); prostate carcinoma (3); Waldenstrom macroglobulinemia (3); Bacterial infection (2); chronic myeloid leukaemia (2); Salmonella Infections (2); anaplastic thyroid cancer (1); bilirubin encephalopathy (1); cervical squamous cell carcinoma (1); hematological malignancies (1); lentivirus infection (1); malaria (1); pancreatic carcinoma (1); pancreatic ductal adenocarcinoma (1); triple-negative breast carcinoma (1).